LATS1 (large tumor suppressor kinase 1)
Diseases named in the same sentence as LATS1 in open-access papers (continued):
Sharing a sentence is not in itself a finding about the gene and the disease.
cardiac disease (1 paper, 2020). "Using gain- and loss-of-function genetic models, it was shown that the Hippo-YAP signaling pathway components Mst1/2, Sav1, Lats1/2, NF2, and downstream transcriptional regulators YAP and Tead1 regulate cardiac gene expression, cardiomyocyte proliferation, and cardiac disease status." (PMID 32938943, 2020).
kidney diseases (1 paper, 2022). "Future studies need to explore strategies (such as modulation of YAP, LATS1/2, and MST1/2 expression) that will help make clinical diagnosis more accurate, more sensitive, and faster to allow assessment of the progress and improve the treatment and prognosis of kidney diseases." (PMID 36483738, 2022).
LATS1 also shares sentences with these, for which no sentence is quoted: head and neck squamous cell carcinoma (4 papers); metastatic tumors (2); pancreatitis (2); acute lymphoblastic leukemia (1); adenoid cystic carcinoma (1); adenoma (1); alveolar rhabdomyosarcoma (1); basal cell carcinoma (1); benign parathyroid tumors (1); carcinoma in situ (1); cervical squamous cell carcinoma (1); cholangiocarcinoma (1); chronic lymphocytic leukemia (1); chronic pancreatitis (1); Disc Degeneration (1); dwarfism (1); endometrial tumors (1); esophageal squamous cell carcinoma (1); Fabry disease (1); Fanconi anemia (1); fibrosis (1); Follicular Cyst (1); gastrointestinal system cancers (1); giant cell tumor (1); Hutchinson-Gilford progeria syndrome (1); hyperlipidaemia (1); infertile (1); lentivirus infection (1); liver fibrosis (1); lymphoma (1).
A further 21 diseases each share a sentence with LATS1 in 1 paper.